PIK3R1 (phosphoinositide-3-kinase regulatory subunit 1)
Diseases named in the same sentence as PIK3R1 in open-access papers (continued):
Sharing a sentence is not in itself a finding about the gene and the disease.
glioma (33 papers, 2012 to 2025). A benign or malignant brain and spinal cord tumor that arises from glial cells (astrocytes, oligodendrocytes, ependymal cells). "Genes from the RTK/PI3K pathway, including PTEN, PIK3R1 in glioma, and ALK, PIK3C2G, ERBB4 in melanoma, showed lower mutation rates in AYAs, reiterating our earlier observation on recurrent genes." (PMID 36433963, 2022). "IDH wildtype gliomas have also shown a high frequency of PIK3R1 mutations." (PMID 40564017, 2025). "One of the three unclassifiable LGNET with FGFR1 p.K656E mutation harbored an accompanying PIK3R1 p.K567E missense mutation, which is a specific variant that has been recurrently found in gliomas and other tumor types [Catalog of Somatic Mutations in Cancer database v91 release]." (PMID 32859279, 2020). "To date, somatic mutations of PIK3R1 in glioma have been well-researched." (PMID 28785028, 2017). "Furthermore, NLRP6-induced glioma progression was abolished when PTEN or PIK3R1 was deficient." (PMID 37770465, 2023). "Among the selected genes, 15 (Araf, Braf, Kras, Ccnd1, Cdk6, Igf1r, Nras, Pik3ca, Pik3r1, Pdgfra, Pdgfrb, Pdgfb, Akt1, Akt2, and Mdm2) were related to glioma and leukemia." (PMID 31523185, 2019). "Activation of PI3K via Pten deletion, PIK3R1 mutations, or constitutively active AKT mutants promotes tumorigenesis in glioma models." (PMID 29975751, 2018). "We found that glioma models harboring alterations in PIK3CA/PIK3R1 and PTEN were highly sensitive to the antitumor effects of DS." (PMID 28423515, 2017). "Furthermore, our analysis revealed that NF1, PIK3R1 and PIK3CA are commonly mutated genes in H3F3A-mutant gliomas (24.6%, 17.7%, and 7.7%, respectively)." (PMID 37524847, 2023). "PIK3R1 has been found to promote the transformation of malignant astrocytes into glioma-like state." (PMID 33042807, 2020). "For example, PIK3R1 is part of the PI3K pathway where it has been demonstrated to be commonly mutated in several cancers and able to drive malignant transformation of astrocytes into a glioma-like state however minimal evidence exists demonstrating a role in determining patient survival." (PMID 31405148, 2019). "On the contrary, 43 driver genes were down-regulated expression and related to favorable clinical outcomes in glioma patients, such as PIK3R1, FLT3, PIK3R1 and RUNX1T1." (PMID 29046615, 2017). "Therefore, we conclude that increased ERBB3 abundance and PIK3R1 expression and decreased ERBB2, FGFR3, and AKT2 expression may explain the improved LGG patient survival in IDH-mutant gliomas compared with IDH-wildtype gliomas." (PMID 27852048, 2017).
gastric cancer (32 papers, 2014 to 2026). A primary or metastatic malignant neoplasm involving the stomach. "Recently, a study indicated that phosphoinositide-3-kinase regulatory subunit 1(PIK3R1)-activated PI3K/protein kinase B (AKT) signaling reduced sensitivity to CDDP in gastric cancer cells by inhibiting cell apoptosis and promoting cell survival." (PMID 38184597, 2024). "Hsa_circ_0000199 enhances cisplatin resistance and gastric cancer (GC) cell survival by promoting the expression of phosphoinositide-3-kinase regulatory subunit 1 (PIK3R1) by sponging miR-198." (PMID 37998329, 2023). "CircRNA AKT3 upregulates PIK3R1 by inhibiting miR-198 to enhance cisplatin resistance (by inhibiting apoptosis and facilitating DNA damage repair) in gastric cancer." (PMID 35615158, 2022). "Specifically, circAKT3, which localizes to and functions in the cytoplasm, modulates CDDP sensitivity by sponging miR-198 that suppresses PIK3R1 expression in gastric cancer." (PMID 33874956, 2021). "For example, NEAT1 can promote prostate cancer by regulating ACSL4 via sponging miR-34a-5p and miR-204-5p, and promotes the growth of gastric cancer cells by regulating the miR-497-5p/PIK3R1 axis." (PMID 33738254, 2021). "For example, circular RNA circAKT3, harboring multiple conserved binding sites for miRNA and is highly expressed in cisplatin-resistance gastric cancer samples, was recently reported to function as a miR-198 sponge to regulate PIK3R1 expression recently." (PMID 32381016, 2020). "For example, miR-479-5p directly targets PIK3R1 in gastric cancer cell and increases cell growth in vitro." (PMID 31938022, 2020). "circ-AKT3 promoted cisplatin resistance in gastric cancer by suppressing miR-198 and upregulating PIK3R1." (PMID 32855967, 2020). "Suppression of Akt1 and PIK3R1 expression using Akt1 and PIK3R1 small hairpin RNA RNAi can inhibit gastric carcinoma cell growth in vitro and in vivo." (PMID 25003395, 2014). "Circular RNA AKT3 could regulate drug resistance in gastric cancer (GC) cells via inhibition of miR-198 and upregulation of PIK3R1." (PMID 37608665, 2024). "Notably, the protein levels of PIK3R1 in cervical cancer, renal cancer, lung cancer, skin cancer, stomach cancer, and testis cancer were lower compared to normal tissues, which is consistent with the results from transcriptional analysis." (PMID 35395865, 2022). "For example, circular RNA AKT3 could inhibit the expression of miR-198 and up-regulate PIK3R1 expression, then enhance cisplatin resistance in gastric cancer." (PMID 32499818, 2020). "However, in contrast to the co-activation of AKT and STAT3 signaling in PIK3R1 loss ovarian cancer cells, the molecular rationale underlying the synergism in the KRAS mutant gastric cancer cells is the activation of STAT3 upon inhibition of PI3K signaling." (PMID 30755611, 2019). "For example, circAKT3 promotes PIK3R1 expression via miR-198 suppression in gastric cancer." (PMID 31438963, 2019). "Conversely, miR-21 is transferred from M2-macrophage to gastric cancer cells through exosomes and inhibits apoptosis of gastric cancer cells by regulating PTEN/phosphoinositide-3-kinase regulatory subunit 1 (Pik3r1, also known as PI3K)/Akt signaling and anti-apoptotic Bcl2 expression." (PMID 29899293, 2018). "MiR-486-5p was also shown to directly inhibit PIK3R1 expression in gastric cancer cells." (PMID 26895105, 2016). "The NEAT1/miR-130/IRF1 axis in gastric cancer, NEAT1/miR-24-3p/LRG1 axis in thoracic aortic aneurysm, NEAT1/miR-324-5p/RAN axis in retinoblastoma and NEAT1/miR-497-5p/PIK3R1 axis in renal tubular oxidative injury have been widely studied." (PMID 39546499, 2024). "A recent study found that miR-486-5p downregulated the expression of PIK3R1, hence activating the PI3K/AKT pathway in human gastric cancer cells." (PMID 36153544, 2022). "In gastric cancer (GC), methylation sequencing and RT-qPCR confirmed that knocking out NSUN2 significantly decreased PIK3R1 and PCYT1A expression levels." (PMID 41462962, 2025).
gastric cancer (continued). "Although statistical analysis displayed that the expression differences of PIK3R1 and PIK3R2 in lung cancer, stomach cancer, or other cancers were not statistically significant, which may be due to the small sample size, their abnormal expression in cancer was distinct." (PMID 35395865, 2022).
hepatocellular carcinoma (28 papers, 2013 to 2025). A malignant tumor that arises from hepatocytes. "Similar findings were reported in a mouse model of hepatocellular carcinoma characterized by liver-specific PIK3R1 deficiency, which resulted in enhanced tumor development." (PMID 40657399, 2025). "As reported in a mice model, loss of PIK3R1 in the liver led to progressive changes of liver pathology and gradually developed into hepatocellular carcinoma with lung metastasis." (PMID 35395865, 2022). "In a murine model with liver-specific PIK3R1 loss, this condition led to development of aggressive hepatocellular cancer." (PMID 24229379, 2013). "In isoniazid-treated HepG2 cells, RNA sequencing analysis has revealed an upregulation of the PIK3R1 gene, mediated by isoniazid through histone modifications, leading to elevated levels of p85α and the activation of the hepatocellular carcinoma-associated PAM pathway." (PMID 40657399, 2025). "Chemoresistance in hepatocellular carcinoma is partially attributed to chemotherapy-induced N-acetyltransferase 10, which significantly upregulates H3K27Ac on the PIK3R1 promoter, thereby activating transcription and driving chemoresistance." (PMID 40657399, 2025). "For instance, PIK3R1 exerts an inhibitory function in hepatocellular carcinoma and renal cancer, while it acts as an oncogene in ovarian and colon cancers, contributing to tumor growth and metastasis." (PMID 38863309, 2024). "For example, PIK3R1 was overexpressed in hepatocellular carcinoma, which promotes cell proliferation and migration capabilities." (PMID 35733630, 2022). "PIK3R1 expression is up-modulated in clinical tissue specimens of hepatocellular carcinoma and knockdown of PIK3R1 represses the malignant biological behaviors of cancer cells." (PMID 34765599, 2021). "Regarding the mechanism underlying miR-128 regulating autophagy, it was reported that miR-128 directly targets PIK3R1 to suppress hepatocellular carcinoma proliferation." (PMID 34646427, 2021). "On the contrary, some studies found the relations of miR-486-5p and PIK3R1 in other cancers: colorectal cancer and hepatocellular carcinoma." (PMID 31402930, 2019). "PIK3R1 has been reported to play a tumor suppressor role in hepatocellular cancer and this tumor suppressor effect is lost in the case of gene underexpression." (PMID 24229379, 2013). "Therefore, the expression pattern and prognostic value of PIK3R1 in hepatocellular carcinoma deserve further exploration based on larger sample sizes and clinical data." (PMID 35395865, 2022). "Moreover, another study has found that PIK3R1 was highly expressed in the majority of hepatocellular carcinoma clinical tissue specimens, and overexpression of PIK3R1 contributed to hepatocellular carcinoma progression." (PMID 35395865, 2022). "It is concluded that FOXA1 promotes cell proliferation and inhibits apoptosis, whereas FOXA1 is also found to suppress hepatocellular carcinoma cell viability and motility by transcriptional inactivation of phosphoinositide-3-kinase regulatory subunit 1 (PIK3R1) in PI3K/Akt signaling." (PMID 34336665, 2021). "The tumor suppressor role of PIK3R1 was also validated in hepatocellular carcinoma (HCC) patients in TCGA analyzed by the Gene Expression Profiling Interactive Analysis (GEPIA) databases (Data not shown)." (PMID 34141708, 2021). "Another study about hepatocellular carcinoma (HCC) showed overexpressed miR-487a happened in poor prognostic patients, which increases cell proliferation by phosphoinositide-3-Kinase regulatory subunit 1 (PIK3R1) induced AKT signaling." (PMID 32792861, 2020). "To explore the key targets and signaling pathways of Ansofaxine hydrochloride for inhibiting hepatocellular carcinoma, we first dock SRC, GRB2, PIK3R1, AKT1, and EGFR, which are in the front of the core genes." (PMID 40809022, 2025). "However, a pair of studies showed that miR-128-3p inhibits hepatocellular carcinoma (HCC) cell proliferation by binding to PIK3R1 and CDC6." (PMID 37700222, 2023).
hepatocellular carcinoma (continued). "Analyses of the mechanism and function revealed that FOXA1 suppresses hepatocellular carcinoma cell viability and motility by inhibiting PI3K/Akt signaling through direct inhibition of PIK3R1 transcription." (PMID 29208003, 2017). "Phosphoinositide-3-kinase, regulatory subunit 1 (PIK3R1) could regulate cancer cell proliferation important for cancer cell proliferation; however, its role in Hepatocellular carcinoma (HCC) remains largely unknown." (PMID 30497511, 2018). "In hepatocellular carcinoma cells HCC, miR-376a is significantly down-regulated and the elevated miRNA-376a repressed cell proliferation and induced apoptosis in HCC cells by targeting p85α and reduced PIK3R1 directly." (PMID 24204780, 2013). "PIK3R1 underexpression might possibly lead to PI3K pathway activation and confer tumor development and progression in humans in a similar way to that observed in a mouse model of hepatocellular cancer." (PMID 24229379, 2013).
prostate carcinoma (28 papers, 2010 to 2026). A carcinoma that arises from epithelial cells of the prostate gland. "PIK3R1 is a tumor suppressor gene involved in growth signaling pathways that is mutated in up to 6 % of prostate cancers." (PMID 40124187, 2025). "Some of the genes that have been linked to the development of prostate cancer are PIK3R1, SRC, STAT3, HSP90AA1, AKT1, MAPK1, SESR1, and AR." (PMID 39114070, 2024). "Analysis of organoid cultures derived from patients with advanced prostate cancer detected mutations in PIK3R1 in 2/7 patients." (PMID 26501081, 2015). "Here we show that expression of the PI3K regulatory subunit p85α protein-encoding gene PIK3R1 is under direct control of androgens and is reduced in prostate carcinoma tissue relative to the normal prostate gland." (PMID 26501081, 2015). "In contrast, in prostate cancers, the truncating mutations were found mainly in the cSH2 domain, suggesting that the localization of PIK3R1 mutations may vary between tumor types and may have different functional consequences." (PMID 39858051, 2025). "In prostate cancer, PIK3R1 is rarely mutated (0.4–1.6% of cases) yet deep deletions occur in 1–6% of patients, which could potentially promote PI3K-AKT-mTOR signaling." (PMID 32630372, 2020). "p85α, encoded by PIK3R1, is reported to be an oncogene in ovarian, colorectal and prostate cancers, so exploring the role of p85α in HCC may provide unique insights into activation of PI3K/AKT pathway." (PMID 30497511, 2018). "Within the prostate-associated protein subset, CDK6 was the most connected node (14 edges), followed by ACVR2B, KMT2A, and PIK3R1, each with 13 edges (which ranks potential biomarkers and their impacts in prostate cancer)." (PMID 41598250, 2026). "For example, PIK3R1 expression level is markedly downregulated in ovarian cancer, lung cancer, prostate cancer, liver, breast and kidney cancers." (PMID 31938022, 2020). "We find that the PIK3R1 gene is directly repressed by androgens and has decreased expression in clinical prostate cancer." (PMID 26501081, 2015). "The four miRNAs regulate PTEN expression post-transcriptionally, and affect the downstream PI3K/Akt pathway via PIK3CA (p110α), PIK3CD (p110δ), PIK3R1 (p85), Akt as well as cyclin D1, thus promote prostate cancer cell proliferation in vitro." (PMID 24098737, 2013). "Indeed, even transient knockdown of PIK3R1 (leading to a partial loss of PIK3R1 mRNA expression) alone was sufficient to induce AKT activation and the proliferation of prostate cancer cells." (PMID 39858051, 2025). "Using the WGS data, we assessed the presence of variants and/or mutations in several genes that are known to be frequently mutated in prostate cancer (BRCA1, BRCA2, RB, PTEN, CDK12, PI3K, ADP-ribose, PIK3GA, PIK3CB and PIK3R1, AKT, CYP17, IGF 1, EGF, and BCL2)." (PMID 36643868, 2022). "In addition, five prostate cancer–associated genes (EGF, PIK3R1, ATM, BRCA1, and BRCA2) with apparent damaging mutations, one of which is a rare mutation in ATM, a possible therapeutic target, further support this claim." (PMID 36643868, 2022). "Besides, prostate cancer organoid lines harboring both PTEN loss and PIK3R1 mutation were sensitive to everolinus and BKM120." (PMID 30219074, 2018). "Interestingly, down-regulation of PIK3R1 in prostate cancer has been linked to reciprocal negative feedback between the AR and PI3K signaling cascades, and PIK3R3 upregulation has been linked to prostate hyperplasia." (PMID 32630372, 2020). "Seven genes (ATM, BCL2, ERN1, FOS, NRAS, PIK3R1, and SP1) were regulated in opposite directions in patients with HD and prostate cancer." (PMID 37298337, 2023). "In addition to PTEN alterations, alterations of other members of the PI3K signaling pathway are frequent in prostate cancer, involving alterations of PI3KCA (13%), PIK3R1 (6%), NF2 (3%), AKT1 (1.5%), and NF1 (1.5%)." (PMID 31366128, 2019). "In prostate cancer, however, activating mutations in PIK3CA or PIK3R1 have not been reported thus far." (PMID 20407443, 2010).
prostate carcinoma (continued). "By analyzing whole-exome sequencing results from an advanced prostate cancer patient cohort, we explored potentially activating alterations in the PI3K pathway and identified oncogenic alterations across the dominant drivers of PI3K signaling (PTEN, PIK3CA, PIK3CB, PIK3R1)." (PMID 34417459, 2021).